DKK1 (dickkopf Wnt signaling pathway inhibitor 1)
Diseases named in the same sentence as DKK1 in open-access papers (continued):
Sharing a sentence is not in itself a finding about the gene and the disease.
colitis (3 papers, 2016 to 2022). Inflammation of the colon. "In line with this, the expression of the WNT inhibitor DKK1 contributed to murine colitis that was improved in DKK1 deficient mice." (PMID 34903876, 2022). "Taken together, these results suggested that IL-1β-primed ERCs exhibited anti-inflammatory effects in colitis through reducing DKK1 sections, which in turn leads to the activation of Wnt/β-catenin signaling." (PMID 34090510, 2021). "In addition, we observed that ERCs downregulated DKK1 expression by IL-1β pre-stimulation, and IL-1β-primed ERCs attenuated the development of colitis." (PMID 34090510, 2021).
COVID-19 (3 papers, 2021 to 2024). A disease caused by infection with severe acute respiratory syndrome coronavirus 2. "Lower DKK1 expression in COVID-19 patients has also been linked to poorer outcomes, possibly indicating a protective effect in MIS-C patients." (PMID 38632526, 2024). "DKK-1 also induces the formation of adipocytes; therefore, its lower levels in placenta could also be linked with the lower leptin levels recorded in mothers who suffered COVID-19 in the current study." (PMID 38610889, 2024). "We used the publicly available single-cell RNAseq dataset GSE12803331 composed of 13 patients (4 healthy, 3 presenting with mild COVID-19 symptoms, and 6 presenting with severe COVID-19 symptoms) to further characterize the expression of DKK1." (PMID 34112877, 2021). "From the analyses of the single-cell data, DKK1 is highly expressed in COVID-19 patients compared to controls, specifically in severe patients and it is expressed by epithelial cells." (PMID 34112877, 2021). "As for bone turnover, placental samples from mothers with COVID-19 showed lower levels of OPG (p < 0.05), while DKK-1 increased compared with the control group (p < 0.05 for both)." (PMID 38610889, 2024).
cutaneous leishmaniasis (3 papers, 2025 to 2026). Leishmaniasis affecting the skin. "This review examines the emerging role of platelet-derived Dickkopf-1 (DKK1), an inhibitor of Wnt signaling, in shaping immunity during cutaneous leishmaniasis and explores its broader implications in other infectious diseases." (PMID 42311685, 2026).
depression (3 papers, 2023 to 2025). "GSK3β is closely associated with the AD proteins PS2 and MAPT and with the depression‐related proteins NR3C1 and DKK‐1." (PMID 37501340, 2024). "Corticosterone also induces DKK‐1 expression via the activation of GRs, and damages neurons resulting in major depression and other stress‐related disorders in mouse models." (PMID 37501340, 2024). "The results indicated that there is a relationship between DVL and the release of AD‐related mediators and expression of the depression‐related glucocorticoid receptor and DKK‐1." (PMID 37501340, 2024).
endometriosis (3 papers, 2015 to 2024). The growth of functional endometrial tissue in anatomic sites outside the uterine body. "Additionally, our study highlights several potential key genes likely involved in the pathogenesis of endometriosis by altering cell migration, such as DKK1, GRB7, MIEN1, PIK3R1, and KRT19." (PMID 39595577, 2024). "Specifically, GREB1 (a GWAS-linked gene induced by WNT signaling) was significantly upregulated while DKK1 (WNT inhibitor) was significantly downregulated in both dStromal early and dStromal mid cells in endometriosis." (PMID 39198675, 2024).
Ewing sarcoma (3 papers, 2016 to 2021). A small round cell tumor that lacks morphologic, immunohistochemical, and electron microscopic evidence of neuroectodermal differentiation. "It has been hypothesized that this decrease in DKK1 expression may contribute to the aggressive and highly malignant behavior of Ewing’s sarcomas." (PMID 27539223, 2016). "In the form of EWS/FLI1 the transcription factor inhibits the expression of DKK1 in Ewing sarcomas but its role in SPN is still unknown." (PMID 27539223, 2016). "Finally, it has also been reported that, in Ewing Sarcoma, DKK-1 constitutes a target of the oncogenic EWSR1-FLI1 chimeric protein, and that DKK-1 inhibition could contribute to progression of tumors of the Ewing family." (PMID 34451907, 2021). "In Ewing’s sarcoma the fusion protein EWS/FLI1 inhibits basal and β-catenin induced transactivation of the DKK1 promoter." (PMID 27539223, 2016).
glomerulosclerosis (3 papers, 2020 to 2024). A hardening of the kidney glomerulus caused by scarring of the blood vessels. "Using GSK-J4 reduces DKK1 expression, thereby ameliorating renal insufficiency, glomerulosclerosis morphological abnormalities, inflammation, and fibrosis in diabetic mice." (PMID 36012674, 2022). "It was confirmed that GSK-J4, via dickkopf-1 (DKK1) modulation, could significantly reduce proteinuria and glomerulosclerosis in diabetic mice." (PMID 36012674, 2022).
Hypercalcemia (3 papers, 2017 to 2023). An abnormally increased calcium concentration in the blood. "Bone-acting factors were present in serum and RANKL, PTHrP and DKK1, key mediators of hypercalcemia and bone loss, were upregulated in Gzmb-HBZ T cells." (PMID 29050201, 2017).
idiopathic pulmonary fibrosis (3 papers, 2021 to 2024). Idiopathic pulmonary fibrosis (IPF) is a nonneoplastic pulmonary disease that is characterized by the formation of scar tissue within the lungs in the absence of any known cause. "Wnt-1 and Wnt-10b were noted to be overexpressed, whereas DKK1 was decreased, which led to the increased nuclear accumulation of β-catenin observed in human tissue samples from systemic scleroderma (SSc), idiopathic pulmonary fibrosis (IPF), and liver cirrhosis." (PMID 34439762, 2021).
knee osteoarthritis (3 papers, 2010 to 2026). "The aim of the present study was to evaluate, for the first time in the literature, both plasma and synovial fluid levels of Dkk-1 in patients with primary knee OA, and examine the possible relationships between plasma and synovial fluid Dkk-1 with the radiographic grading of knee osteoarthritis." (PMID 21062498, 2010). "In knee osteoarthritis cartilage, high expression of RUNX2 and DKK-1 leads to chondrocyte hypertrophy and cartilage extracellular matrix decomposition, promoting cartilage degeneration." (PMID 36915153, 2023).
laryngeal carcinoma (3 papers, 2015 to 2021). Carcinoma that arises from the laryngeal epithelium. "The limitation of this study is that the mechanism that the NK4 gene affects the occurrence and development of laryngeal cancer may be related to the regulation of the DKK1/Wnt1/β-Catenin related pathways, which needs to be demonstrated by further experiments." (PMID 34970492, 2021). "Accordingly, western blot assay suggested that the expression of DKK1, vimentin and β-catenin was significantly decreased after YAP downregulated treatment, thereby indicating that YAP mediated the EMT programme and the Wnt/β-catenin signalling pathway in carcinoma of the larynx." (PMID 31269911, 2019).
liver diseases (3 papers, 2016 to 2025). "In our study, statistically significant cutoff values for DKK1 and mRNA CKAP4 variables were determined to distinguish kidney diseases from liver diseases (P < .001)." (PMID 40922300, 2025). "DKK1 was significantly overexpressed in patients with HCC than in the healthy controls and patients with liver diseases except HCC (all P < 0.05)." (PMID 38012711, 2023). "In particular, in AFP-negative HCC cases, DKK1 may be more effective in differentiating HCC from nonmalignant liver diseases." (PMID 40922300, 2025).
memory impairment (3 papers, 2019 to 2023). "Induction of DKK1 expression in the hippocampus triggers synapse loss, synaptic dysfunction and memory impairment, all of which can be fully restored by reactivation of Wnt/β-catenin signaling after cessation of DKK1 expression in the hippocampus." (PMID 31801553, 2019). "The results of NORT and MWMT also proved the alleviating effect of Ex-4 on the cognitive and memory impairment in T2D mice, and such alleviation was ineffective after addition of DKK1 which blocked the activation of the Wnt/β-catenin signaling." (PMID 37667187, 2023). "DKK1 level in hippocampal tissues of mice reveals an increase with age extension, accompanied by the impairment of spatial memory; however, the knockdown of DKK1 in hippocampal tissues improves the spatial memory of mice, thereby reversing the aging-induced memory impairment." (PMID 32390823, 2020).
nephritis (3 papers, 2014 to 2017). Inflammation of renal tissue. "DKK-1 levels in human SLE correlate most closely with bone erosion and nephritis, perhaps indicating an autoregulatory feedback loop during disease progression." (PMID 27548498, 2016).
ovarian tumors (3 papers, 2020 to 2024). "Generally, DKK1 expression levels were decreased in ovarian tumors compared with normal ovarian surface epithelium (p=1.6E-8) and decreased in tumor stroma compared with normal stoma (p=3.8E-2) based on the CSIOVDB database." (PMID 33613114, 2021). "When BRCA2mt ovarian tumors were compared with BRCA1mt tumors, eight genes (NOTUM, SFRP5, RNF43, ZNRF3, DKK1, DKK4, NKD1, and AXIN2) that negatively regulate Wnt signaling were upregulated in BRCA2mt tumors." (PMID 39028933, 2024).
parasite infection (3 papers, 2023 to 2025). "Previously, we demonstrated that treatment with a DKK1 inhibitor diminished leukocyte accumulation at the inflammatory site following parasite infection." (PMID 40502169, 2025). "While DKK1 induces type 2 inflammation via CD4+ T cells in allergen-induced asthma and a parasitic infection model, whether DKK1 regulates other immune cells that play a central role in inflammation and tissue repair remains elusive." (PMID 38162655, 2023). "Notably, DKK1 levels were comparable in the LRP6NKO and BALB/c mice in response to infection, indicating that PMN activation is the major pathway for DKK1 in promoting parasitemia." (PMID 39502693, 2024).
parathyroid tumor (3 papers, 2007 to 2020). "Parathormone (PTH) mRNA levels were positively modulated by miR-372 overexpression in parathyroid tumor cells, while the Wnt pathway was inhibited in the miR-372-expressing parathyroid tumor cells, through the miR-372-induced upregulation of DKK1." (PMID 33066578, 2020). "An aberrantly spliced internally truncated LRP5 receptor (LRP5Δ666–809, LRP5Δ) was shown recently to be resistant to DKK1 inhibition, and was required for β-catenin accumulation in hyperparathyroid tumors and parathyroid tumor growth." (PMID 19158955, 2009). "Therefore, we examined the effect of DKK1, which is expressed in parathyroid tumors (unpublished data) on WNT3-stimulated β-catenin activity in sHPT-1 cells." (PMID 18044981, 2007).
polycystic ovary syndrome (3 papers, 2019 to 2025). A disorder that manifests as multiple cysts on the ovaries. "We identified CBX2 regulated genes associated with polycystic ovary syndrome (PCOS) such as TGFβ, MAP3K15 and DKK1, as well as genes implicated in premature ovarian failure (POF) (i.e. POF1B, BMP15 and HOXA13) and the pituitary deficiency (i.e. LHX4 and KISS1)." (PMID 31745224, 2019). "In polycystic ovary syndrome (PCOS), overexpression of DKK1 reduced the apoptosis rate of granulosa cells; moreover, overactivation of SIRT2 and increased deacetylation of DKK1 were detected in cells from PCOS rats." (PMID 40664665, 2025).
preeclampsia (3 papers, 2013 to 2025). Preeclampsia is a hypertensive disorder of pregnancy that is characterized by new-onset hypertension with proteinuria presenting after 20 weeks of gestation, and depending on mild or severe forms may initially present with severe headache, visual disturbances, and hyperreflexia. "Additionally, this list included several genes associated with preeclampsia (PE) such as TIMP3, Wnt regulator DKK1, fibronectin FN1, cannabinoid receptor CNR1, neurokinin receptor TAC3, retinol binding protein RBP4, and prolactin PRL." (PMID 30131724, 2018). "Besides, we analysed the β-catenin and DKK1 expression between patients with preterm and term preeclampsia." (PMID 23452984, 2013). "All proteins selected by PLSKO have been reported to be related to preeclampsia, including SERPINE1, HSPB1, CXCL10, DKK1." (PMID 40880285, 2025). "Beta-catenin and DKK1 are involved in a variety of biological processes; however, their expression in the placenta with severe preeclampsia (PE) has not been elucidated." (PMID 23452984, 2013).
prostate tumor (3 papers, 2007 to 2025). "Dkk3 has recently been shown to be down-regulated in human prostate tumor samples, and DKK1 treatment can inhibit prostate tumor cell growth." (PMID 18478098, 2008). "This certainly seems probable since a recent study has demonstrated that prostate tumours-expressing high levels of Dkk-1 produce more extensive local bone destruction compared to controls that express lower levels." (PMID 17987039, 2007).
rhabdomyosarcoma (3 papers, 2017 to 2022). A rare aggressive malignant mesenchymal neoplasm arising from skeletal muscle. "Pal and colleagues described a role for EHMT2-mediated suppression of Wnt signaling in Rhabdomyosarcoma through activation of DKK1." (PMID 35983994, 2022). "Here, for the first time, we report the analysis of the therapeutic potential of DKK-1 pharmaceutical inhibition in rhabdomyosarcoma, the most common soft tissue sarcoma in children." (PMID 34884726, 2021). "Only a few works have studied the genetic inhibition and function of DKK-1 in rhabdomyosarcoma." (PMID 34884726, 2021). "In rhabdomyosarcoma (RMS), it has been shown that a reduction of DKK-1 expression results in myogenic differentiation in vitro." (PMID 34884726, 2021).
sacroiliitis (3 papers, 2015 to 2022). "Multivariate analysis revealed a significant positive association of DKK-1 serum level and female gender (p = 0.03), CRP level (p = 0.006), SOST serum level (p = 0.002) and the presence of sacroiliitis on radiography (p = 0.05)." (PMID 26313358, 2015). "In multivariate analysis, DKK-1 serum levels were associated with male gender (p = 0.03), CRP level (p = 0.006), SOST serum level (p = 0.002) and presence of sacroiliitis on radiography (p = 0.05)." (PMID 26313358, 2015). "DKK-1 serum level was associated but not significantly with sacroiliitis on radiography (mean 33.02 ± 16.47 vs 29.93 ± 15.28, p = 0.056)." (PMID 26313358, 2015). "Univariate analyses revealed high DKK-1 level (Ptrend = 0.056) and low SOST level (P = 0.02) among patients with sacroiliitis on radiography." (PMID 26313358, 2015). "Bone erosions, sacroiliitis and SCJ were correlated with elevated serum levels of Dkk-1." (PMID 36532039, 2022).
spondylitis (3 papers, 2010 to 2017). The inflammation of a vertebra. "Our data support this proposed elevated Wnt signalling in spondylitis with markedly decreased levels of the Wnt inhibitors DKK1 and SOST, the first such demonstration in a mouse model of SpA or AS." (PMID 23171658, 2012). "This corresponds well with the previous finding that expression of Dkk1 and SOST was reduced in the spine of a proteoglycan-induced spondylitis (PGISp) mouse model of SpA, compared with controls." (PMID 28882159, 2017).
unstable angina pectoris (3 papers, 2017 to 2024). "Furthermore, patients with unstable angina pectoris exhibited higher serum DKK1 levels than those with stable angina pectoris and healthy individuals." (PMID 38175715, 2024).
viral infection (3 papers, 2023 to 2026). "Beyond leishmaniasis, accumulating evidence suggests that platelet activation and DKK1 release may also participate in the immunopathology of fungal and viral infections." (PMID 42311685, 2026).
vitiligo (3 papers, 2023 to 2025). Generalized well circumscribed patches of leukoderma that are generally distributed over symmetric body locations and is due to autoimmune destruction of melanocytes. "The significant decrease in DKK1 production by GPNMB knockdown suggests that GPNMB is a key molecule regulating the WNT/β-catenin signaling pathway in vitiligo KCs." (PMID 39947468, 2025). "Common factors that contribute to AA and vitiligo include oxidative stress, autophagy, type 2 cytokines, and the Wnt/β-catenin pathway (e.g., dickkopf 1 (DKK1))." (PMID 38673994, 2024). "DKK1 is highly expressed in the dermis of vitiligo lesions and cultured fibroblasts from vitiligo lesions, suggesting a role of DKK1 and other Wnt signaling pathways in vitiligo pathogenesis." (PMID 38673994, 2024). "Dickkopf-related protein 1 (DKK1), an inhibitor of WNT signaling that regulates cell adhesion and migration, is overexpressed in the dermis of patients with vitiligo." (PMID 36980277, 2023).
alopecia areata (2 papers, 2023 to 2024). Loss of scalp and body hair involving microscopically inflammatory patchy areas. "Our study focused on investigating the expression of DKK1 in alopecia areata (AA), a condition characterised by significant increases in the DKK1 levels in human and mouse ASCs." (PMID 37991164, 2024). "A study in 2019 revealed that the expression of DKK-1 was significantly increased in patients with AGA and alopecia areata (AA), suggesting that DKK-1 plays a certain role in these hair-related diseases." (PMID 37510231, 2023). "As a result, DKK1‐KO‐ASCs exhibit an inhibitory effect on alopecia areata." (PMID 37991164, 2024).
amyloid (2 papers, 2014 to 2018). "Dickkopf-1 (Dkk1), an antagonist of Wnt components, has been reported to decrease the synapse number of hippocampal neurons and participate in the amyloid-induced reduction in the synapse number." (PMID 24999626, 2014). "Finally, we report that pharmacological inhibition of the Aβ-Dkk1-Aβ positive feedback loop with the drug fasudil can restore the balance between Wnt pathways, prevent dendritic spine withdrawal in vitro, and reduce Aβ load in vivo in mice with advanced amyloid pathology." (PMID 30232325, 2018).
breast invasive carcinoma (2 papers, 2017 to 2024). "DKK1 levels, however, were substantially reduced in several cancers, including prostate adenocarcinoma (PRAD), kidney renal papillary cell carcinoma (KIRP), breast invasive carcinoma (BRCA), kidney chromophobe (KICH), and bladder urothelial carcinoma (BLCA)." (PMID 38376441, 2024).
cardiac hypertrophy (2 papers, 2020 to 2025). "In conclusion, our research revealed TUG1 targeted miR‐34a to block the inhibitory effects of miR‐34a on DKK1, thereby inhibiting the activation of Wnt/β‐catenin signalling and alleviating cardiac hypertrophy." (PMID 32057178, 2020). "Up‐regulation of miR‐34a targeted DKK1 to block the inhibitory effects of DKK1 on Wnt/β‐catenin signalling, inducing cardiac hypertrophy." (PMID 32057178, 2020). "All of these results indicated that TUG1 overexpression alleviated TAC‐induced cardiac hypertrophy and dysfunction through TUG1/miR‐34a/DKK1/Wnt‐β‐catenin signalling in vivo." (PMID 32057178, 2020). "Indeed, to the best of our knowledge, this was the first time to report DKK1 exerted an inhibitory effect of the Wnt/β‐catenin signalling pathway in PE‐ and TAC surgery‐induced cardiac hypertrophy." (PMID 32057178, 2020).
chronic hepatitis (2 papers, 2014 to 2016). An active inflammatory process affecting the liver for more than six months. "Chronic hepatitis tissue samples exhibited significantly higher levels of methylation as compared to normal controls (p = 0.0136 & 0.0084 for SFRP2 & DKK1 respectively, Mann–Whitney U test)." (PMID 24947038, 2014).
coloboma (2 papers, 2017 to 2018). An abnormality in which a part of a structure in one or both eyes is missing. "For example, overexpression of the Wnt inhibitor Dkk1 results in loss of dorsal ocular gene expression, and mutation of the Wnt receptor FZD5 (thought to function as a receptor for both canonical and non-canonical Wnts) causes inferior coloboma." (PMID 29522511, 2018).
femoral head osteonecrosis (2 papers, 2020 to 2024). "In our investigation of osteonecrosis of the femoral head (ONFH), individuals with ONFH exhibited heightened DKK1 expression in bone tissue and serum, alongside increased apoptosis markers." (PMID 38773377, 2024).